SKIL (SKI like proto-oncogene)
Diseases named in the same sentence as SKIL in open-access papers:
SKIL is named in the same sentence as 64 diseases in open-access papers, as found by Europe PMC text mining. Sharing a sentence is not in itself a finding about the gene and the disease. The quoted sentences say what the papers report.
breast carcinoma (18 papers, 2013 to 2026). "For example, Transcriptional activity of SMAD2/SMAD3:SMAD4 heterotrimer involved in the degradation of SKI/SKIL, thus causing malignant transformation in breast cancer." (PMID 38652712, 2024). "For example, upregulation or amplification of SKIL has been associated with breast cancer, squamous cell carcinoma of the esophagus, prostate cancer, squamous cell carcinoma of the head and neck, and non-small cell lung cancer." (PMID 36553500, 2022). "Analysis of The Cancer Genome Atlas (TCGA) datasets indicated that SKIL is highly expressed in multiple breast cancer subtypes." (PMID 41828672, 2026). "Another recent study has proposed that SKIL can interact with and promote the activity of estrogen receptor α in the nuclei of breast carcinoma cells." (PMID 25749039, 2015). "SKIL promoted breast cancer tumourigenesis by enhancing the activity of TAZ." (PMID 38468490, 2024). "CCND1, SKIL and CD46 primarily involved in early breast cancer progression and immune evasion were predicted to be dysregulated by circRNA‐miRNA interaction." (PMID 33544410, 2021). "Even though their time-dependent effects have not been characterized in detail, SKIL and SKI are known to be repressors of the TGFβ-induced gene expression response, which control EMT in non-small cell lung cancer and metastasis in breast cancer cells." (PMID 39542693, 2025).
renal fibrosis (9 papers, 2014 to 2025). A final common manifestation of a wide variety of chronic kidney diseases characterized by glomerulosclerosis and tubulointerstitial fibrosis. "Loss of SKIL expression appears to exacerbate progressive renal fibrosis in DKD19." (PMID 36585417, 2022). "Bone morphogenetic protein-7 (BMP-7) ameliorates renal fibrosis by increasing the expression of SKIL in renal tubular epithelial cells." (PMID 36585417, 2022).
colorectal cancer (7 papers, 2006 to 2025). A primary or metastatic malignant neoplasm that affects the colon or rectum. "MiR‐32‐5p also presents low expression and involve in the ceRNA axis of SNHG14/miR‐32‐5p/SKIL in colorectal cancer." (PMID 33448691, 2020). "NSUN2 promotes the growth of colorectal cancer cells by increasing m5C modification on SKIL mRNA and enhancing its interaction with YBX1, which stabilizes SKIL mRNA and increases Transcriptional co-activator with PDZ-binding motif (TAZ) expression." (PMID 39791162, 2025).
ovarian carcinoma (7 papers, 2009 to 2022). A malignant neoplasm originating from the surface ovarian epithelium. "Genes identified to be aberrantly expressed at the 3q26.2 locus (i.e. SnoN/SkiL) have been implicated in ovarian cancer pathophysiology." (PMID 23621864, 2013). "In addition, SKIL has been associated with leukemia, ovarian cancer, and squamous cell carcinoma of the lung." (PMID 36553500, 2022). "This region contains the MECOM, SnoN/SKiL, and ECT2 genes all of which have been implicated in ovarian cancer pathogenesis." (PMID 23289505, 2013). "However, PLSCR1 regulates SnoN/SkiL-dependent pathway in ovarian cancer cells." (PMID 35422844, 2022). "For example, ATO induces SnoN/SkiL, an inhibitory TGF-β1 regulator by affecting Smad3 nuclear transportation in ovarian carcinoma cells." (PMID 24762191, 2014). "Our earlier published studies indicate that the 3q26.2 chromosomal region is highly amplified in ovarian cancers and harbors various oncogenes including EVI1, PKCι, and SnoN/SkiL." (PMID 23621864, 2013).
lung carcinoma (5 papers, 2013 to 2024). "Correlation analysis also showed a positive correlation between SKIL mRNA and protein expression levels in human lung cancer cell lines." (PMID 33268765, 2020). "This trend was different from the observations in SKIL expression in lung cancer cell lines." (PMID 33268765, 2020).
prostate carcinoma (4 papers, 2014 to 2022). A carcinoma that arises from epithelial cells of the prostate gland. "Transcriptome sequencing of these samples revealed a SLC45A3-SKIL fusion in LuCaP-77 and a MIPEP-SKIL fusion in the clinical sample, confirming SKIL as a recurrent 3′ fusion partner in prostate cancer." (PMID 25749039, 2015). "Our findings highlight SKIL as an oncogene and potential therapeutic target in 1-2% of prostate cancers, amounting to an estimated 10,000 cancer diagnoses per year worldwide." (PMID 25749039, 2015). "SKIL fusions were found in 6 of 540 (1.1%) prostate cancers and 1 of 27 (3.7%) cell lines and xenografts." (PMID 25749039, 2015). "In this study, we performed transcriptome and low-coverage whole genome sequencing on 28 untreated and 13 castration resistant prostate cancers, and identified a new prostate cancer subtype characterized by activating rearrangements of the SMAD inhibitor SKIL." (PMID 25749039, 2015). "Interestingly, all 5 SKIL-positive clinical samples with clinical information (two TCGA samples lacked clinical data) contained a Gleason grade 5 component or represented metastatic prostate cancer, suggesting that SKIL-activating alterations may associate with high-grade prostate cancer." (PMID 25749039, 2015). "To better understand the biological role of SKIL in prostate cancer cells, we knocked SKIL down in PC-3 cells using two different siRNA, and observed reduced cell growth, invasiveness, and colony formation relative to scrambled siRNA." (PMID 25749039, 2015). "The role of SKIL as a prostate cancer oncogene lends support to recent studies on the role of TGF-β signaling as a rate-limiting step in prostate cancer progression." (PMID 25749039, 2015). "SKIL knockdown led to growth arrest in PC-3 and LNCaP cell line models of prostate cancer, and its overexpression led to increased invasiveness in RWPE-1 cells." (PMID 25749039, 2015). "The discovery of SKIL-activating rearrangements in both untreated and castration resistant prostate cancers suggests that SKIL rearrangements may represent an early event in prostate tumorigenesis." (PMID 25749039, 2015). "By inspection, we also identified at least 10 additional transcription factors within 500 kb of 9 other GWAS loci, that are also reasonable candidates for contributing to prostate cancer risk: SOX13, ZFP36L2, ATOH8, DLX1 & DLX2 (same locus), GATA2, SKIL, SP8, ASCL2, and DPF1." (PMID 24497837, 2014). "More recently, a novel fusion event was reported in about 1% of prostate cancer cases, juxtaposing exons 1 or 2 of TMPRSS2 to exon 2 of the SMAD inhibitor and oncogenic factor SKIL and leading to its overexpression." (PMID 33634124, 2021). "Nonetheless, SKIL provides an intriguing new molecular target for personalized therapy, and highlights the role of TGF-β signaling in prostate cancer progression." (PMID 25749039, 2015). "Here we report the discovery of a new prostate cancer subtype characterized by rearrangements juxtaposing the SMAD inhibitor SKIL with androgen regulated promoters, leading to increased SKIL expression." (PMID 25749039, 2015). "These SLC45A3-ETS fusions and the fusions involving SKIL have not been reported in prostate cancer cell lines." (PMID 33634124, 2021). "This hypothesis is supported by the fact that SKIL rearrangements appear to be mutually exclusive with ETS fusions, which represent a known early event in prostate cancer progression." (PMID 25749039, 2015).
schizophrenia (3 papers, 2019 to 2024). A major psychotic disorder characterized by abnormalities in the perception or expression of reality. "Their real-time quantitative PCR analysis illuminated patients with schizophrenia have the overexpression of miR-124-3p, the under expression of SKIL and EGR1 in the blood compared with controls, and after a 12-week treatment, the direction of change of miR-124-3p and SKIL mRNA levels were reversed." (PMID 35136033, 2022). "As for the association between the SKIL and schizophrenia, a previous study used the network coexpression analysis in three microarray datasets, and established a miRNA-TF-gene network related to schizophrenia, including the EGR1-miR-124-3p-SKIL feed-forward loop." (PMID 35136033, 2022).
squamous cell carcinoma of the esophagus (3 papers, 2010 to 2022). "Finally, a previous study has shown miR-720 transcribed downstream from the co-transcriptional factor Ski-related novel gene (SnoN/SKIL) in esophageal squamous cell carcinoma (ESCC) cells, and that down-regulation of SnoN decreased the levels of miR-720 as well as ESCC cell proliferation." (PMID 24386225, 2013).
astrocytic tumor (1 paper, 2025). A glial tumor of the brain or spinal cord showing astrocytic differentiation. "Elevated expression of SMAD1, SMAD3, and SKIL emerged as strong prognostic indicators, underscoring their potential as biomarkers and therapeutic targets in astrocytic tumors." (PMID 40869118, 2025). "Figure 2illustrates the promoter methylation status of six genes involved in the TGF-β signaling pathway—SKIL, SMAD1, SMAD3, SMAD4, BMP2, and MAPK1—across astrocytic tumors of increasing malignancy (grades G2, G3, and G4)." (PMID 40869118, 2025).
astrocytomas (1 paper, 2025). "Compared to G2 tumors, high-grade astrocytomas (G3 and G4) exhibited elevated levels of SKIL, SMAD1, SMAD3, BMP2, and MAPK1, with most differences reaching statistical significance (p < 0.05)." (PMID 40869118, 2025). "In this study, we present multi-level evidence demonstrating that key mediators of the TGF-β signaling pathway—SKIL, BMP2, SMAD1, SMAD3, SMAD4, and MAPK1—are consistently upregulated in high-grade astrocytomas." (PMID 40869118, 2025).
atherosclerosis (1 paper, 2022). A disease characterized by the build-up of fatty material and calcium deposition in the arterial wall resulting in partial or complete occlusion of the arterial lumen. "For instance, hypermethylation in the PTPRN2 gene has been associated with metabolic syndrome in African American population, and hypermethylation of the SKIL gene has been associated with atherosclerosis." (PMID 36457109, 2022). "Top DMPs were annotated to the PTPRN2, SKIL, and KCNT1 genes, which have been reported in relation to cardiometabolic risk factors, atherosclerosis, and sodium-potassium handling." (PMID 36457109, 2022).
cancers of the skin (1 paper, 2015). "Overexpression of either SKI or SKIL in chicken embryo fibroblasts is sufficient to induce oncogenic transformation, and SKIL expression is elevated in many human cancers, including cancers of the skin, breast, colon and blood." (PMID 25749039, 2015).
glioma (1 paper, 2025). A benign or malignant brain and spinal cord tumor that arises from glial cells (astrocytes, oligodendrocytes, ependymal cells). "SKIL, while canonically a repressor, may act in gliomas through alternative protein–protein interactions not yet fully elucidated but potentially relevant to chromatin accessibility or transcriptional pausing." (PMID 40869118, 2025).
oral cancer (1 paper, 2014).
ovarian serous adenocarcinoma (1 paper, 2009). An adenocarcinoma that arises from the ovary and is characterized by the presence of malignant epithelial cells that, in well differentiated tumors, resemble the epithelium of the fallopian tube or, in poorly differentiated tumors, show anaplastic features and marked nuclear atypia. "The LCM data set shows over-expression of CLDN11, MYNN, PRKCI, and SKIL in ovarian serous adenocarcinoma." (PMID 19419571, 2009).
prostate adenocarcinoma (1 paper, 2015). "Analysis of transcriptome sequencing data from the Cancer Genome Atlas (TCGA) prostate adenocarcinoma project revealed additional SKIL-activating rearrangements in 4 of 423 samples, with concomitant SKIL overexpression." (PMID 25749039, 2015).
cancer (26 papers, 2006 to 2024). A tumor composed of atypical neoplastic, often pleomorphic cells that invade other tissues. "In addition, to the best of our knowledge, our study is the first to show roles of SKIL in immune escape of cancer cells, and to illustrate the underlying mechanisms which involved upregulation of TAZ and autophagy, and subsequent inhibition on STING pathway." (PMID 33268765, 2020). "SKIL has been reported to play a dual role in different cancers; it has both anticancer and carcinogenic activities depending on other genetic changes in the tumor." (PMID 34479589, 2021). "The 3q26 locus is amplified in several cancer types, and SKIL (along with TLOC1) has been highlighted as the most potent oncogene in this region." (PMID 25749039, 2015). "SAIC also identified many other cancer driver genes within individual chromosomes (ST 3), such as SKIL, CDK4, PIK3CA, PTEN, FGD4, FGFR1." (PMID 22839576, 2012). "Current studies showed that SKIL has both pro-cancer and tumor suppressor functions." (PMID 38951569, 2024). "However, it served as a cancer suppressor in the early stages of some human cancers, which aroused our concern to investigate the role of SKIL in CRC." (PMID 34479589, 2021). "Overall, silencing of SKIL resulted in inhibited malignant phenotypes (viability, proliferation, invasion, migration, EMT, and cancer stem cell viability) in CALU-3 and NCI-H520." (PMID 33268765, 2020). "Expression levels of cancer stem cell markers (CD44, CD133, SOX2, OCT3/4, and NANOG) were also decreased after silencing of SKIL in CALU-3 and NCI-H520." (PMID 33268765, 2020). "We found two major types of complexes that are affected by miRNAs during cancer progression; the first contains SMAD3, SMAD2, SMAD4, SMAD6, FOXO1, HOXC8, and SKIL, which are connected to AKT1, which is in turn a key modulator of TGF-B signaling pathway." (PMID 24391925, 2013). "PTEN expression was not aberrantly low in any of the 7 SKIL-positive cases, and only 1 of 4 SKIL-positive cancers in the TCGA cohort showed evidence of PTEN deletion, suggesting that SKIL rearrangements do not require combined PTEN loss." (PMID 25749039, 2015).
tumor (26 papers, 2006 to 2025). "Indeed, prior studies have linked SKIL overexpression to apoptosis resistance in other tumor types, underscoring its potential as a therapeutic target." (PMID 40869118, 2025). "Conversely, the upregulation of SKIL, which promotes MC proliferation and cytokine production, suggests a potential anti-tumor effect in the TME." (PMID 40061903, 2025). "Specifically, the upregulation of SMAD1, SMAD3, SMAD4, BMP2, MAPK1, and SKIL—driven by promoter hypomethylation and reduced expression of tumor-suppressive microRNAs—leads to enhanced activation of both canonical and non-canonical branches of TGF-β signaling." (PMID 40869118, 2025). "The relative expression level of SKIL in tumor tissues of NSCLC patients exhibited a positive correlation with the expression level of TAZ, a transcriptional regulator." (PMID 38566036, 2024). "The results showed that NSUN2 knockdown inhibited tumour growth and decreased tumour weight and Ki67 expression levels, while SKIL overexpression rescued these effects." (PMID 38468490, 2024). "By inhibiting SKIL expression in cancer cells, the adaptive immunity of tumor cells can be activated, thereby enhancing the efficacy of anti-tumor immunotherapy and introducing a novel treatment strategy for NSCLC." (PMID 38566036, 2024). "The co-repressors SKI and SKIL play important roles in a number of different cellular processes including proliferation, differentiation, transformation, and tumor progression." (PMID 33416497, 2021). "The results showed that tumour tissues with high NSUN2 expression had higher levels of SKIL." (PMID 38468490, 2024). "In contrast, some studies have suggested that SKIL plays a tumour suppressor role." (PMID 38468490, 2024). "Knockdown experiments suggested that SMAD4 was not necessary, but we subsequently showed that tumor cells deleted for SMAD4 or containing mutations in SMAD4 that abolish interactions with activated R-SMADs, abrogated TGF-β-induced degradation of SKI/SKIL." (PMID 33416497, 2021). "In CRC tumour tissues, the protein expression levels of NSUN2 and SKIL showed a significant positive correlation." (PMID 38468490, 2024). "SKIL, also known as SnoN, is a mediator of the TGF‐β signalling pathway and plays oncogenic or tumour‐suppressive roles in epithelial tissues." (PMID 38468490, 2024). "SMAD7 and SKIL are well known as negative regulators of TGF-β signaling, and KLF10 is believed to play a crucial role as a tumor suppressor with unique tissue-specific functions mediated by TGF-β signaling." (PMID 32629802, 2020). "SKIL and PMEPA1 mRNA expression in tumor tissues was significantly increased compared with controls and not correlated with protein levels in the blood of paired HCC patients." (PMID 28230858, 2017). "CNAs detected in LS+ tumours but not in LS−/TC+ tumours, include 3q26 gain, a locus likely to include SKIL because the average SKIL copy number was greater in LS+ tumours than in LS−/TC+ tumours (P = 0.0060)." (PMID 23866769, 2013). "In contrast, the tumor-specific cluster C3 appears less differentiated with features typical of CD56brightCD16neg NK cells (NCAM1, CD2, CD27, SELL, CD69) as well as a signature of tissue residency (CD69 and ITGA1) and of TGF-β-induced genes (SMAD7, TGFB1, PMEP1, SKIL)." (PMID 41145419, 2025).
SKIL also shares sentences with these, for which no sentence is quoted: Hepatic fibrosis (4 papers); Diabetic Nephropathy (3); esophageal cancer (3); hepatocellular carcinoma (3); non-small cell lung carcinoma (3); pancreatic cancer (3); acute promyelocytic leukemia (2); adenocarcinoma (2); Barrett esophagus (2); colon cancers (2); diabetes (2); malignant melanoma (2); pulmonary fibrosis (2); triple-negative breast carcinoma (2); bladder cancer (1); breast ductal adenocarcinoma (1); breast tumours (1); cholestasis (1); chronic pancreatitis (1); colorectal tumours (1); dysplasia (1); fetal growth restriction (1); fibrosis (1); hepatic cirrhosis (1); Hyperglycemia (1); invasive breast carcinoma (1); keloid (1); leukemia (1); liver cancer (1); lung adenocarcinoma (1).
A further 16 diseases each share a sentence with SKIL in 1 paper.